F2RL1 (F2R like trypsin receptor 1)
Diseases named in the same sentence as F2RL1 in open-access papers:
F2RL1 is named in the same sentence as 111 diseases in open-access papers, as found by Europe PMC text mining. Sharing a sentence is not in itself a finding about the gene and the disease. The quoted sentences say what the papers report.
breast carcinoma (8 papers, 2013 to 2024). "Connecting these findings, another study reported a significant link of F2RL1, F3, and VEGF-A expression in the clinical setting of primary breast cancer, where patients with phosphorylated F3 and F2RL1-expressed tumor tissue specimen are prone to recurrence." (PMID 34066023, 2021). "Importantly, PRSS3/MTG linked to F2RL1 (also known as PAR2), was reported to modulate inflammation and tumorigenesis in several cancer types, such as colon cancer and breast cancer." (PMID 35480112, 2022).
pancreatic cancer (8 papers, 2015 to 2023). "Currently, the mechanism of F2RL1 in the malignant progression of pancreatic cancer remains unclear, and more scientific evidence is needed." (PMID 36900234, 2023). "Moreover, F2RL1 has been identified as a reliable immune-related biomarker with prognostic significance in pancreatic cancer (PC) and colorectal cancer (CRC)." (PMID 37814309, 2023).
colon carcinoma (7 papers, 2001 to 2024). "By regression analysis, 6 immune-related DEGs (AEN, F2RL1, NR3C2, PPARGC1A, LGALS4, and XDH) were identified as potential prognostic factors, of which AEN, LGALS4, and XDH were used to construct a risk score model, which can effectively predict overall survival (OS) in colon cancer patients." (PMID 36589748, 2022).
colorectal cancer (7 papers, 2013 to 2026). A primary or metastatic malignant neoplasm that affects the colon or rectum. "F2RL1 was found could be one of thirteen immune-related genes as prognostic signatures in colorectal cancer." (PMID 35830566, 2022).
asthma (6 papers, 2015 to 2024). "Since we are interested to understand the regulation of T2 inflammation in asthma, we studied if F2RL1 rs1529505 is associated with TH2 cells, TH2 cells’ ligand PGD2, cytokines IL-13 and CCL5, a T cell chemoattractant." (PMID 38308375, 2024). "Since F2RL1 (the gene encoding PAR-2) polymorphisms affect PAR-2 expression, we hypothesize they may affect asthma severity." (PMID 38308375, 2024).
diabetes (6 papers, 2016 to 2026). "We have also identified that several well-characterised GPCRs (CASR, GPRC5B, GPR119, F2RL1), which are either current drug targets or under evaluation as potential diabetes therapeutic targets, are highly expressed in both human and mouse islets." (PMID 28422162, 2017).
Pruritus (6 papers, 2014 to 2025). Pruritus is an itch or a sensation that makes a person want to scratch. "Proteinase activated receptor 2 (F2RL1) is expressed in the epidermis of individuals with atopic dermatitis and plays an important role in pruritus pathogenesis." (PMID 28869563, 2017).
liver fibrosis (5 papers, 2018 to 2025). "F2r mRNA expression increased significantly at the early and progressive stages of liver fibrosis, whereas the F2rl1 mRNA level that was unchanged in acute and after 2.5-week liver injury increased at the 4th, 6th, and 7th weeks of CCl4 treatment, suggesting a delayed induction." (PMID 34566641, 2021).
Obesity (4 papers, 2016 to 2024). Accumulation of substantial excess body fat. "We found that obesity was associated with increased expression of the PAR2 gene, F2RL1, and decreased expression of the LPL gene." (PMID 38973609, 2024). "F2RL1 is intrinsically associated with signaling cascades potentiated by the interaction of low-density lipoproteins (LDL) with macrophages and is further implicated in the promotion of diet-induced obesity and fat inflammation." (PMID 37814309, 2023).
hepatocellular carcinoma (3 papers, 2016 to 2021). A malignant tumor that arises from hepatocytes. "The clinicopathological findings are further supported by work in vitro and in model systems: LX-2 hepatic stellate cells-expressing F2RL1 enhance tumor growth via angiogenesis in vivo using a xenograft of hepatocellular carcinoma model and in an intestinal tumor model." (PMID 34066023, 2021).
oral cancers (3 papers, 2021 to 2022). "Also, the abnormal activation of PAR2, also known as coagulation factor II (thrombin) receptor-like 1 (F2RL1) drives several pathophysiologic processes in the oral cavity, including oral cancers, as PAR2 promotes oral squamous cell carcinoma growth/progression in vitro." (PMID 34290715, 2021).
cervical cancer (2 papers, 2021 to 2022). A primary or metastatic malignant neoplasm involving the cervix. "F2RL1 is overexpressed in cervical cancer cell lines and significantly correlated with poor OS." (PMID 33671013, 2021).
gastric cancer (2 papers, 2019 to 2025). A primary or metastatic malignant neoplasm involving the stomach. "Evidence for functional roles in cancer cells of GPCRs that are highly expressed and overexpressed in solid tumors and cancer cells include findings for PAR1/F2R in BRCA, gastric cancer, colon cancer, and melanoma cells and for PAR2/F2RL1 in melanoma, BRCA, and colon cancer cells." (PMID 31765370, 2019).
intestinal tumor (2 papers, 2021 to 2022). "F2RL1, also known as protease-activated receptor 2 (PAR2), has been reported to be associated with the occurrence and development of lung adenocarcinoma and intestinal tumors." (PMID 36091041, 2022).
lung adenocarcinoma (2 papers, 2022). A carcinoma that arises from the lung and is characterized by the presence of malignant glandular epithelial cells. "MRNA expression levels of TIMP1, S100P, HMMR, F2RL1, KRT6A, and SLC2A1 were significantly increased in lung adenocarcinoma cell lines compared to16HBE, which were consistent with our bioinformatics analysis results." (PMID 35830566, 2022).
ovarian carcinoma (2 papers, 2020 to 2024). A malignant neoplasm originating from the surface ovarian epithelium. "In this communication, we show the central role played by Par2/f2rl1 as a predictor of ovarian cancer." (PMID 38275417, 2024). "RT-PCR analyses of several aggressive ovarian cancer cell lines revealed high expression levels of Par2/f2rl1 and Par4/f2rl3." (PMID 38275417, 2024). "Indeed, we demonstrate that when Par2/f2rl1 is knocked down, the peritoneal dissemination and formation of ovarian cancer foci are effectively inhibited." (PMID 38275417, 2024).
Sepsis (2 papers, 2020 to 2024). Sepsis is defined as life-threatening organ dysfunction caused by a dysregulated host response to infection. "At a log2FC>2 (adjusted P < 0.05) MAPK related genes F2rl1, Adm (marked as multi, as it was picked up for term searches “metabolic,” “hypoxia,” and “MAPK”), Mapk4, Gdf15, Dusp10, and Dusp8 were up-regulated in Isoflurane-Sepsis compared to only 2 genes in the Propofol-Sepsis group." (PMID 33392215, 2020).
vitiligo (2 papers, 2019 to 2021). Generalized well circumscribed patches of leukoderma that are generally distributed over symmetric body locations and is due to autoimmune destruction of melanocytes. "We also validated the DNA methylation levels of the HIF-1α and F2RL1 promoter to explore the potential pathogenic mechanisms regarding CD8+ T cells in vitiligo." (PMID 31885781, 2019). "The mRNA and protein expression levels of PIK3CB, HIF-1α, and F2RL1 were all elevated in CD8+ T cells from peripheral blood in vitiligo." (PMID 31885781, 2019). "In the current study, the mRNA and protein expression levels of F2RL1 were increased in CD8+ T cells from PBMCs in vitiligo." (PMID 31885781, 2019). "However, the DNA methylation levels of the F2RL1 promoter showed non significance in vitiligo patients compared to controls." (PMID 31885781, 2019). "Furthermore, the study found that F2RL1 may be a new driver of vitiligo, closely related to reactive oxygen species, and contributes to the activation and/or migration of melanocyte‐specific CD8 + T cells." (PMID 33169883, 2021). "Consequently, we speculate that hsa‐miR‐340‐5p/hsa‐miR‐20a‐5p could jointly modulate the expression of F2RL1, thereby affecting the development of vitiligo." (PMID 33169883, 2021). "In conclusion, HIF-1α, F2RL1, and PIK3CB may act as novel drivers for vitiligo, which are all closely associated with reactive oxygen species and possibly contribute to the activation and/or migration of melanocyte-specific CD8+ T cells in vitiligo." (PMID 31885781, 2019). "Previous studies have chronicled that the expression of F2RL1 mRNA and protein in CD8 + T cells in PBMCs with vitiligo is increased." (PMID 33169883, 2021). "Ultimately, we found that the mRNA and protein levels of HIF-1α, F2RL1, and PIK3CB genes were all elevated in the CD8+ T cells in vitiligo." (PMID 31885781, 2019). "Given that F2RL1 is also a DNA methylation-sensitive gene, we also validated the DNA methylation status of the F2RL1 promoter to investigate the mechanism of the overexpression of F2RL1 in CD8+ T cells from PBMCs in vitiligo patients." (PMID 31885781, 2019). "However, the DNA methylation level of the F2RL1 promoter showed no variation in vitiligo patients." (PMID 31885781, 2019).
acute myeloid leukemia (1 paper, 2019). Acute myeloid leukemia (AML) is a group of neoplasms arising from precursor cells committed to the myeloid cell-line differentiation. "F2RL1 may act as novel acute myeloid leukemia subsets that are meaning for treatment guidance." (PMID 31558162, 2019).
injury (1 paper, 2021). Damage inflicted on the body as the direct or indirect result of an external force, with or without disruption of structural continuity. "Activation of PAR2 is intimately related to the coagulation cascade, and mice lacking the Par2/F2rl1 gene show reduced fibrin deposition in bleomycin-induced lung injury and glomerular nephritis." (PMID 33776786, 2021).
keratoconus (1 paper, 2023). A degenerative, structural disorder of the eye, characterized by a cone-shaped protrusion of the cornea. "Ultimately, it was found that the chemokine receptors CCR2 and CCR5, as well as F2RL1 and CXCL5, may be involved in the immune regulation process of keratoconus." (PMID 37965330, 2023).
kidney failure (1 paper, 2022). An acute or chronic condition that is characterized by the inability of the kidneys to adequately filter the blood. "Additionally, kidney failure markers, namely Lcn2 (lipocalin 2), F2rl1 (coagulation factor 2 receptor-like 1), and Plat (plasminogen activator inhibitor-1), were upregulated (Cluster IV)." (PMID 35764881, 2022).
kidney inflammation (1 paper, 2024). "In addition, Col1a1‐ or Emr1‐positive cells were present near the F2rl1‐positive tubular cells, suggesting a plausible role for PAR2 in kidney inflammation and fibrosis." (PMID 38687090, 2024).
tongue cancer (1 paper, 2021). A malignant neoplasm affecting the tongue. "The level of F2RL1 mRNA was five times higher in the tongue cancer than in the matched tongue tissue (3.0 ± 0.4 in cancer tongue versus 0.6 ± 0.2 in normal tongue)." (PMID 34572924, 2021). "We measured F2RL1 mRNA, with RNAscope® in situ hybridization, in a human tongue cancer and compared it to contralateral unaffected tongue in the same patient (i.e., matched)." (PMID 34572924, 2021).
tumor (39 papers, 2006 to 2025). "Finally, the risk score was calculated by the following formula: tumor-associated endothelial signature score = 0.180855332*ADD1 + 0.059530341*ALOX12 + 0.145361104 *CXCL10 - 0.081730252*F2RL1 + 0.001225741*ITGAX − 0.004914148*MET." (PMID 37719845, 2023). "For the assessment of the relative impact of Par2/f2rl1 on pro-tumor signaling, we knocked down Par2 using shRNA-Par2 in colon-cancer-cell lines (i.e., HCT116 and HT29)." (PMID 40141421, 2025). "F2R-like Trypsin Receptor 1 (F2RL1), as a G-protein-coupled receptor, can be activated by serine proteases and plays a key role in tumor progression." (PMID 36900234, 2023). "We have confirmed that the upregulation of F2RL1 in PDAC tumors can significantly promote tumor proliferation, invasion, and migration." (PMID 36900234, 2023). "An intriguing finding is that both mRNA and protein levels of F2RL1 were increased in both the tumor cells and normal cells after ESC treatment." (PMID 31367256, 2019). "Genetic ablation of F2RL1 from the stromal compartment inhibited primary tumor growth and was accompanied by reduced vascularization in primary tumors and a reduction in tube formation of vascular endothelial cells in vitro." (PMID 29165389, 2017). "Silencing F2RL1 in a PDAC cell line by RNA interference or genetically ablating it from the stromal compartment dramatically suppressed the growth of subcutaneous tumour xenografts and of orthotopically growing primary tumours, respectively." (PMID 27248167, 2016). "F2RL1 encodes PAR2, a G-protein-coupled receptor known to downregulate type I IFN responses and STAT1 signaling 62, leading to the polarization of macrophages towards an M2-like, tumor-promoting phenotype 63." (PMID 38577601, 2024). "Moreover, it has been reported that the enrichment of F2RL1 in the tumor matrix region is increased, which is also similar to our results, suggesting that it mediates TME matrix remodeling to further drive tumor malignant progression." (PMID 36900234, 2023). "Several immune-related genes were shared across tumor types, with seven genes (CASP3, F2RL1, CD22, RORC, PLA2G6, SYCP1, MAP3K5) common to all four histologies." (PMID 40621458, 2025). "The eight genes (CAMK2N1, WNT7A, F2RL1, AREG, DEFB1, CNFN, TGFBI, and CAV1) included in the signature have been extensively studied and are known to be involved in tumor progression and EMT process." (PMID 37907576, 2023). "The mRNA levels of TEK, BMP1, AR, SLC11A1, SLC40A1, and F2RL1 were significantly downregulated in tumor cells compared with normal cells, and CX3CL1 and RNASE2 were upregulated in tumor cells." (PMID 35004689, 2021). "TCGA and Genotype-Tissue Expression (GTEx) database analysis showed that F2RL1 was highly expressed in PDAC tumor tissues compared with non-tumor tissues (NAT)." (PMID 36900234, 2023). "At the cellular level, deploy CRISPR/Cas9 knock-out/knock-in and CRISPRa/i of F2RL1 with biosensor read-outs for Gq/11, G12/13, ERK, NF-κB, and β-arrestin (BRET/FRET) to map biased PAR-2 transduction under EGCG, FXa, trypsin/tryptase, and tumor-derived protease milieus." (PMID 41226835, 2025). "Therefore, whether there are subsets of cells with F2RL1 as a marker in the TME of PDAC as a bridge or not, the interaction between the tumor and TME remains to be further explored." (PMID 36900234, 2023).
cancer (31 papers, 2014 to 2026). A tumor composed of atypical neoplastic, often pleomorphic cells that invade other tissues. "Analysis of large cancer datasets reveals that F2RL1 expression is among the highest in colon adenocarcinoma compared to numerous other cancer types, and significantly higher than other PAR family members (F2R/PAR1, F2RL2/PAR3, F2RL3/PAR4) within CRC tissues." (PMID 41002416, 2025). "Protease-activated receptor-2 (PAR2) also known as F2RL1 is a G protein-coupled receptor that intimately correlates with cancer occurrence." (PMID 33968158, 2021). "Of them, PAR2 (also known as F2RL1) was observed to have significantly poor promoter methylation but highly expressed PAR2 mRNA in cancer tissue." (PMID 33968158, 2021). "Previous works have indicated that protease-activated receptor 2 (PAR2, encoded by F2RL1) functions in the regulation of carcinogenesis in diverse cancers." (PMID 32724813, 2020). "F2RL1, also known as Fc receptor-like 2, has been studied in the context of cancer." (PMID 39869563, 2025). "To probe the role of PAR2 in human NSCLC, we first compared the expression level of PAR2 (F2RL1) in human lung tumor tissues and normal lung tissues from The Cancer Genome Atlas (TCGA) and The Genotype-Tissue Expression (GTEX) databases using online analysis tools." (PMID 33967759, 2021). "Thus, we speculated that F2RL1 is involved in the cross-talk between ESCs and the F2RL1-expressing cells including, cancer cells and normal cells." (PMID 31367256, 2019). "For example, PAR-2 (F2RL1) is overexpressed in some ovarian cancer tissues mainly inducing cell migration, and PAR-1 (F2R) has been found to be abundant in invasive carcinomas, but not in the healthy ovarian epithelium, driving FAK signaling and promoting cancer malignancy." (PMID 35625966, 2022). "Given that F2RL1 is not only a cell surface receptor but is also related to PI3K signaling in various physiological and pathological processes, such as inflammation and cancer, its upregulation may be a key to the role of the ESCMe." (PMID 31367256, 2019).
infection (8 papers, 2017 to 2024). The state of being infected such as from the introduction of a foreign agent such as serum, vaccine, antigenic substance or organism. "Although DTB was unable to induce these genes on its own, with the exception of F2RL1, it amplified their expression upon infection with EHV-4." (PMID 38793627, 2024).
F2RL1 also shares sentences with these, for which no sentence is quoted: atopic dermatitis (4 papers); osteoarthritis (4); prostate carcinoma (4); colitis (3); COVID-19 (3); endothelial dysfunction (3); glioblastoma (3); inflammation (3); Insulin resistance (3); irritable bowel syndrome (3); lung carcinoma (3); atherosclerosis (2); autoimmune disease (2); chronic periodontitis (2); Depression (2); eosinophilia (2); fibrosis (2); glomerulosclerosis (2); inflammatory skin disease (2); lung disease (2); lupus nephritis (2); melanoma (2); myocardial infarction (2); Netherton syndrome (2); non-alcoholic steatohepatitis (2); pancreatitis (2); rheumatoid arthritis (2); acute lymphoblastic leukemia (1); acute pancreatitis (1); alcoholic hepatitis (1).
A further 54 diseases each share a sentence with F2RL1 in 1 paper.